PPARG (peroxisome proliferator activated receptor gamma)
Diseases named in the same sentence as PPARG in open-access papers (continued):
Sharing a sentence is not in itself a finding about the gene and the disease.
Obesity (continued). "In summary, this work demonstrated that B. pilosa and GHT suppressed adipogenesis and lipid content in adipocytes and/or animals via the down-regulation of the Egr2, C/EBPs and PPARγ pathways, suggesting a novel application of B. pilosa and GHT against obesity." (PMID 27063434, 2016). "As to that, when the organism reaches a lipid level threshold lipotoxicity shows up, PPARG is no more capable of lipid handling, and the harmful hormonal environment of obesity starts to spread through the organism." (PMID 27579030, 2016). "In this setting, our results strongly support that PPARγ activation by partial agonists, devoid of full agonism-related unfavourable effects, may be a strategy to induce browning of WAT and hence to treat obesity and diabetes." (PMID 27138164, 2016). "Is obesity, as cancer does with vitamin D, acting as a negative epigenetic driver when it comes to PPARG signalling?" (PMID 27579030, 2016). "Noteworthy, PPARγ is downregulated by AGE and TNFα, overproduced in obesity and type 2 diabetes." (PMID 25361524, 2014). "The associations of 23 SNPs located within 17 candidate genes (MTHFR, PPARγ, LPL, INSIG, TCF7L2, FTO, KCNJ11, JAZF1, CDKN2A/B, ADIPOQ, WFS1, CDKAL1, IGF2BP2, KCNQ1, MTNR1B, IRS1, ACE) with overweight and obesity, diabetes, metabolic phenotypes, and MetS were examined in both studies." (PMID 24959828, 2014). "As another example, abscisic acid increased PPARγ activity independent of its ligand binding mechanism and reduced obesity-related inflammation and promoted glucose tolerance in db/db mice." (PMID 24498211, 2014). "In contrast to full PPARγ agonists, partial PPARγ agonists mitigate insulin resistance and hyperglycemia in rodent models of obesity without increasing adiposity and cardiac weight." (PMID 24498211, 2014). "This study suggests that treating obesity by increasing energy expenditure as a result of brown adipose thermogenesis is more likely to be successful by combined drug therapy aimed at stimulating both PKA and PPARγ signalling pathways." (PMID 23554809, 2013). "In a mouse model setting of high caloric uptake alternative activation of macrophages was not possible without PPARγ expression and therefore affected individuals were more prone to obesity and insulin resistance." (PMID 23554810, 2013). "On the other hand, mice that lack PPARγ specifically within the CNS are resistant to dietary-induced obesity and do not increase feeding or show improvements in hepatic insulin sensitivity when administered PPARγ agonists." (PMID 23550218, 2013). "Investigation of the manner in which SAE supplementation reduces the epididymal fat pad weight revealed that it suppresses the expression of several proteins related to adipogenesis genes, including SREBP-1, PPARγ and FAS, indicating that it exerts an anti-obesity effect by inhibiting adipogenesis." (PMID 23181109, 2012). "In cellular models, MEHP induces adipogenesis by modulating PPARγ activity, suggesting that DEHP could promote obesity in vivo if its MEHP metabolite reaches adipose tissue." (PMID 20123618, 2010). "Although PPARγ is a well-characterized regulator of energy metabolism, the relationship between PPARγ expression and obesity is not clear." (PMID 21182758, 2010). "DEHP-treated mice were protected from diet-induced obesity via PPARα-dependent activation of hepatic fatty acid catabolism, whereas the activity of neither PPARβ nor PPARγ was affected." (PMID 20123618, 2010). "Cinnamon, a widely used spice in food preparation and traditional antidiabetic remedy, is found to activate PPARγ and α, resulting in improved insulin resistance, reduced fasted glucose, FFA, LDL-c, and AST levels in high-caloric diet-induced obesity (DIO) and db/db mice in its water extract form." (PMID 19096709, 2008). "In spite of its vital rolein adipogenesis and lipogenesis, PPARγ expression itselfis not strongly influenced during obesity." (PMID 17389767, 2007).
Obesity (continued). "In addition, methods to increase circulating adiponectin levels including PPARγ agonists or methods leading to upregulation of adiponectin receptors and/or development of specific adiponectin receptor agonists (e.g. osmotin), could prove beneficial in several obesity related malignancies." (PMID 16570048, 2006). "While our findings highlight the anti‐obesity potential of E. conferta extract, further research is needed to clarify its molecular mechanisms, particularly its role in thermogenesis, adipocyte differentiation, and metabolic pathways (e.g., AMPK, PPARγ, and UCP1)." (PMID 40444128, 2025). "Furthermore, piceatannol, a natural stilbene compound, exerted anti-obesity effects by activating AMPK and inhibiting lipogenic proteins such as C/EBPα, PPARγ, and FAS, while altering gut microbiota composition by increasing Lactobacillus and decreasing Bacteroidetes." (PMID 41305647, 2025). "Conversely, impaired PPARγ signalling or dysregulated VLCFA metabolism may contribute to ectopic lipid accumulation, chronic inflammation and the development of obesity‐related metabolic disorders such as obesity and type 2 diabetes." (PMID 40968591, 2025). "TLR/MyD88 is a classic signaling inflammatory response that also involves in obesity development and is inhibited by the overexpression of PPARγ via the negative control of the expression of TLR4, and then activates the expression of CD36 for promoting fatty acid uptake and fat accumulation." (PMID 40045630, 2025). "These include, but are not restricted to, the roles of hypothalamic ceramides in obesity-induced pubertal acceleration in females, as well as the role of hypothalamic PPARγ in the modulation of the female reproductive axis and its perturbation by obesogenic diets." (PMID 39290326, 2024). "Literature on the relationship between BPA substitutes and obesity was identified through PubMed and Google Scholar, utilizing the search terms “BPA substitutes”, “bisphenol analogues”, “BPS”, “BPF”, “BPAF”, “obesity”, “obesogens”, “adipogenesis”, “PPARγ”, and “adipocyte differentiation”." (PMID 37529602, 2023). "In conclusion, the present study reveals a previously unrecognized role of diosmin, a conventional drug features long-time clinical use and safeness, in improving insulin sensitivity by blocking PPARγ phosphorylation and reducing obesity without the side effects of classic PPARγ full agonists." (PMID 36841479, 2023). "However, with the exception of PPARγ inhibitors for the treatment of obesity-related diabetes, most of them have not been approved to treat obesity." (PMID 37435495, 2023). "Adipocyte differentiation, a critical event in the progression of obesity, is an intricate process tightly controlled by various transcription factors, including the members of the CCAAT/enhancer binding protein (C/EBP) family and peroxisome proliferator-activated receptor γ (PPARγ)." (PMID 36978888, 2023). "Thus, capsaicin signaling in obesity and fat metabolism is mainly described as TRPV1-dependent, although some studies presented TRPV1-independent actions, including activation of PPARγ." (PMID 37892544, 2023). "Recent studies suggest that ellagic acid, ACYs and their derivatives might regulate the molecular mechanisms of the liver to work against high-fat diet-induced obesity by diminishing the expression of the hepatic molecular factors SREBP-1c and PPARγ, which are involved in the storage of fat and TGs." (PMID 36678224, 2023). "In order to explore the specific regulatory pathway and mechanism of obesity-induced insulin resistance on macrophages, RNA in the upper chamber was collected in the ADSC-PM co-culture model for PCR detection, and the changes in RNA level in the PPARγ/NF-κB pathway were mainly detected." (PMID 37049846, 2023).
Obesity (continued). "Given the ability of TBT to activate some nuclear receptors, such as retinoid X receptors (RXRs) and PPARγ that are involved in adipogenesis, it was expected that TBT may increase the incidence of obesity and it is, thus, currently considered as a potent inducer of adipogenesis in vertebrates." (PMID 36073672, 2023). "miR-27a can inhibit the expression of PPARγ, acting as a negative obesity regulator." (PMID 35647185, 2022). "Therefore, insights into various signaling pathways, energy-sensing proteins (e.g., AMPK), genes, and their transcription factors that directly interact with PPARγ and CEBP family members are needed to combat abnormal adipose tissue development during the obesity pandemic." (PMID 36676057, 2022). "Despite the obesity-dependent effects of cilostazol on PCSK9 expression, we observed similar effects on the expression of AMPKα and PPARγ, suggesting that mechanisms beyond AMPK/PPARγ activation may be at play." (PMID 36077166, 2022). "Therefore, moderately decreased PPARγ activity is expected to improve insulin resistance and increase bone mass without inducing obesity." (PMID 33494317, 2021). "The beneficial effects of VCE-004.8 on obesity might not be exclusively related to PPARγ activation." (PMID 33498245, 2021). "Though this would suggest that DCs play a deleterious role in obesity, Macdougall and colleagues revealed that VAT conventional DCs subsets actively suppress AT inflammation and promote insulin sensitivity in homeostatic lean conditions via PPARγ and the Wnt/β-catenin pathway." (PMID 34613819, 2021). "In summary, we have provided evidence for a direct transcriptional regulation of SetD7 by PPARγ, and this molecular interaction is manifested during a transient phase of adaptive β-cell response following Px as well as during metabolic stress of HFD-induced obesity and insulin resistance." (PMID 34592314, 2021). "Thus, we hypothesized that PPARγ activation alters the PVAT microenvironment, thereby creating a favorable environment for the attenuation of arterial stiffening in obesity." (PMID 33781257, 2021). "PPARγ may activate expression of the Nrf2 gene and is one of the target genes of Nrf2 signaling (Lee, 2017) but their link in obesity is not obvious." (PMID 34602925, 2021). "Therefore, in an attempt to realize the molecules involved in the pathogenesis of obesity, here, we aimed to evaluate the expression of MALAT1 and TUG1, as well as plausible target genes (PPARγ, PGC1α, SREBP-1c, FAS, and ACC), in VAT and SAT from obese women compared to normal-weight subjects." (PMID 32368256, 2020). "Based on these observations, our study revealed that PML-RARα interacts with PPARγ to disrupt the PPARγ/RXR heterodimer and promote PPARγ ubiquitination and degradation, which may partially explain the obesity and dyslipidemia in newly diagnosed patients with APL that is driven by PML-RARα." (PMID 32929351, 2020). "This study demonstrates that human obesity provokes senescence and diminishes functionality in adipose tissue-derived MSC in comparison to MSC from non-obese controls, suggested by reduced MSC proliferation, expression of the differentiation-dependent factor PPARγ, and pro-angiogenic efficacy." (PMID 32274385, 2020). "Finally, it has been found that obesity does not impair PPARγ expression in adipose tissue (Kuryłowicz, A, unpublished data)." (PMID 32102233, 2020). "Additionally, formononetin, via direct interaction with PPARγ, was found to increase the expression of ucp1 in primary cultures of mouse adipocytes, while its administration to C57BL/6J mice was found to prevent the development of diet-induced obesity." (PMID 32102233, 2020). "Moreover, a number of candidate genes previously linked through GWAS to T2DM and obesity were found to be differentially expressed in the adipose tissue from discordant twins, including PPARG, GLIS family zinc finger 3 (GLIS3) (T2DM), vascular endothelial growth factor A (VEGFA), and IRS1 (obesity)." (PMID 32653024, 2020).
Obesity (continued). "Since the regulator of PPARγ expression is also reported to represent another approach to the treatment of insulin resistance, unidentified molecule(s) secreted in EPS-CM sheds light on the possible mechanism by which exercise prevents obesity and type 2 diabetes." (PMID 32756599, 2020). "Therefore, the purpose of the current study was to verify: 1) if exercise reduced chemerin and CMKLR1in the peripheral metabolic organs (not only serum chemerin) of obesity and diabetes rats; 2) if exercise-induced decreases of chemerin/CMKLR1 were mediated by PPARγ in the diabetes rats." (PMID 30873215, 2019). "Interestingly, by modulating PPARγ and adipocyte differentiation, COUP-TFII could influence the onset of obesity and diabetes." (PMID 31906104, 2019). "Application of the peroxisome proliferator activated receptor gamma (PPARγ) Ligand rosiglitazone further increased the leptin concentrations in BAL, suggesting that treatment of obesity-related type II diabetes may result in higher leptin levels in the lung system." (PMID 30832310, 2019). "Thus, the combined results from our in vivo and in vitro experiments suggest that PPARγ might be a target of PD to affect adipogenesis and lipid metabolism in HFD-induced obesity." (PMID 31828124, 2019). "Interestingly, under persistent over-nutrition, adipocyte hyperplasia decreases the availability of β-catenin ligands for cDC1, while expression of PPARγ in cDC2 is reduced, suggesting a possible mechanism for the pro-inflammatory switch of VAT-cDCs in obesity." (PMID 29514067, 2018). "In an obesity and hyperglycemia animal model, thiazolidinedione derived partial PPARγ agonist GQ-16 increased UCP-1 protein expression in interscapular brown adipose tissue (BAT) and in epididymal and inguinal white adipose tissue (WAT) to induce WAT browning and treat obesity." (PMID 29849705, 2018). "Sequence analysis revealed a PPARγ response element within the chemerin (RARRES2) promoter; thus, insulin-sensitising drugs that activate PPARγ might be beneficial for the treatment of obesity and T2DM." (PMID 29848608, 2018). "With a known function in lipid and glucose metabolism as well as a role in adipogenesis, adipose PPARG expression levels (both isoforms 1 and 2) were investigated in terms of a potential regulation of these genes by PCOS status alone or in combination with obesity." (PMID 28303117, 2017). "Therefore, we concluded that PTX3 could promote the progression of obesity by regulating the expression levels of adipocyte differentiation markers (AP2, PPARγ, CEBP/α, and CEBP/β)." (PMID 28770376, 2017). "Increases in PPARγ posttranslational phosphorylation at serine residues induced by various kinases such as CDK5, extracellular signal-regulated kinase-1/2 and c-Jun N-terminal kinase were reported to be involved in the pathogenesis of insulin resistance, inflammation and obesity." (PMID 28811832, 2017). "Down regulation of PPARγ could provide protection from HFD induced inflammation and obesity." (PMID 26752997, 2016). "As Pparγ upstream factors such as CDK5 are considered as new molecular targets for insulin resistance and other metabolic diseases, mechanism studies of these compounds may provide new molecular targets for obesity and obesity-related metabolic diseases." (PMID 27611793, 2016). "In particular, this study demonstrates that OLE exerts beneficial effects against obesity by overexpressing sirtuin 1 (SIRT-1), peroxisome proliferator-activated receptor alpha (PPARα), and peroxisome proliferator-activated receptor gamma (PPARγ), coactivator 1 alpha (Pgc-1α)." (PMID 27303302, 2016). "In our recent studies, Firemaster® 550 (FM550), a FR replacement for pentabromodiphenyl ethers (pentaBDEs), activated PPARγ and initiated adipocyte differentiation in vitro, which may explain why perinatal exposure to FM550 in rats led to obesity and glucose sensitivity." (PMID 25314719, 2015).
Obesity (continued). "Interestingly, many dietary components like tocopherol, linoleic acid, curcumin and resveratrol upregulate PPARγ expression with no reported side effects in chronic diseases like obesity, cardiovascular diseases, colon cancer, and diabetes." (PMID 23389305, 2013). "This was hypothesised to identify genes that were up regulated during β-cell expansion during obesity in the case of the ob/ob, which failed to occur in a PPARγ-dependent model such as the POKO mouse." (PMID 22208362, 2011). "Taken together,PPARG does not seem to be a major locus for obesity in our population." (PMID 18657264, 2008). "Given that PPARγ plays an essential role in the regulation of adipocyte differentiation and lipid storage, its full activation may not be appropriate for the treatment of obesity." (PMID 41007669, 2025). "Importantly, we found the derivate of the potent PPARγ antagonist GW9662, BZ26 inhibited the reprogramming of mature adipocytes in the visceral fat of HFD-fed mice into CAA-like cells and inhibited the proliferation and invasion of obesity-related breast cancer." (PMID 37649895, 2023). "Moreover, they also found that the expressions of adipogenic markers lipoprotein lipase and peroxisome proliferator-activated receptor γ (PPARγ) are not significantly changed in proliferating obese BMSCs, suggesting unaffected adipogenic lineage commitment under obesity status." (PMID 36902259, 2023). "Interestingly, PPARG expression did not correlate with weight or BMI, which suggests that the obesity effects on bone adiposity might imply ZEB1 modulation rather than major adipogenesis inducer PPARG." (PMID 36890579, 2023). "Our results showed that the PPARγ, C/EBPα, FABP4, and FAS genes were significantly downregulated in CA-treated mice, suggesting that CA may have the ability to reduce lipid accumulation and further alleviate obesity by restraining adipogenesis and lipid synthesis." (PMID 36839338, 2023). "Obesity and nutritional factors influence the expression of PPARγ in human adipocytes and the existence of conditions, such as type two diabetes, once the expression of PPARγ and CEBPA is related negatively to fat cell size in non-obese men with type two diabetes." (PMID 36676057, 2022). "Several other placental genes upregulated by obesity at term (PPARγ, SCD1, CACT, OCTN2, COT) were not significantly altered in early pregnancy, which may indicate a cumulative effect of the obese milieu on placental lipid metabolism pathways throughout gestation." (PMID 36371454, 2022). "Cells isolated from elderly subjects with or without obesity were significantly impaired in their capacity to differentiate into adipocytes, as revealed by Oil Red O staining of neutral lipids and by the gene expression of common adipogenic markers (PPARG, FABP4, LPL, PLIN1, and FASN)." (PMID 35811457, 2022). "The idea of EDCs as factors in obesity did not crystallize until it was recognized that certain EDCs could activate nuclear hormone receptors important for the development of white adipocytes, such as peroxisome proliferator–activated receptor γ (PPARγ)." (PMID 32067051, 2020). "We found that the Ccny mRNA level of the white adipocytes from the mice with HFD-induced obesity was significantly higher than that of the non-obese mice that consumed a normal diet; and the similar situation was also found for the adipogenesis-specific marker PPARγ." (PMID 26161966, 2015). "Therefore, suppression, rather than elimination of PPARγ expression, may be a better way to prevent obesity." (PMID 21760932, 2011). "Indeed, we recently identified A-2819G SNP in PPARG promoter and observed a significant association with T2DM and proliferative retinopathy in diabetic females whereas no linkage disequilibrium with Pro12Ala nor association with obesity was observed." (PMID 20871817, 2010). "In turn, PPARG and other mitochondrial-rated enzymes are shown to be governed by FOXO1 in this type of obesity and not in stress-induced obesity." (PMID 39062927, 2024).